RPS29P14 (ribosomal protein S29 pseudogene 14)
Synonyms: RPS29_3_802
Gene: Processed pseudogene on chromosome 7 (33,036,212 to 33,036,382, reverse strand). Ensembl gene ENSG00000229054.
Diseases named in the same sentence as RPS29P14 in open-access papers:
RPS29P14 is named in the same sentence as 1 disease in open-access papers, as found by Europe PMC text mining. Sharing a sentence is not in itself a finding about the gene and the disease. The quoted sentences say what the papers report.
tumor (1 paper, 2012). "LOC100129599, also known as ribosomal protein S29 pseudogene 14 (RPS29P14), is a pseudogene, and noncoding RNAs transcribed from pseudogenes have been implicated in tumor progression previously." (PMID 23118918, 2012).